ENSG00000252840
Synonyms: LOC124900437
Gene: Small nucleolar RNA gene on chromosome 1 (151,527,831 to 151,527,938, reverse strand). Ensembl gene ENSG00000252840.
Gene Ontology:
Biological process: RNA processing
Cellular component: nucleolus
Homologues: Orthologues: rat LOC120100371 (81% identical), mouse Gm22622 (78% identical), mouse Gm22723 (77% identical), rat LOC120101247 (72% identical), rat LOC120101248 (72% identical), rat Snora44 (66% identical). Paralogues in human: SNORA44 (80% identical).